COPS8 (COP9 signalosome subunit 8)
Description:
Component of the COP9 signalosome complex (CSN), a complex involved in various cellular and developmental processes. The CSN complex is an essential regulator of the ubiquitin (Ubl) conjugation pathway by mediating the deneddylation of the cullin subunits of SCF-type E3 ligase complexes, leading to decrease the Ubl ligase activity of SCF-type complexes such as SCF, CSA or DDB2.
Synonyms: SGN8; CSN8; COP9; MGC1297
Tractability: PROTAC: ubiquitination databases record sites on it; its protein half-life has been measured.
Gene: Protein-coding gene on chromosome 2 (237,085,882 to 237,100,474, forward strand). Ensembl gene ENSG00000198612.
Subcellular location: Cytoplasm; Nucleus
Subcellular location (Human Protein Atlas): Nucleoplasm; Cytosol
Pathways (Reactome):
DNA Repair: DNA Damage Recognition in GG-NER; Formation of TC-NER Pre-Incision Complex
Metabolism of proteins: Neddylation
Vesicle-mediated transport: Cargo recognition for clathrin-mediated endocytosis
Gene Ontology:
Molecular function: protein binding
Biological process: activation of NF-kappaB-inducing kinase activity; negative regulation of cell population proliferation; protein deneddylation; protein phosphorylation; protein neddylation; regulation of protein neddylation; COP9 signalosome assembly
Cellular component: COP9 signalosome; cytoplasm; cytosol; extracellular exosome; nucleoplasm; nucleus; perinuclear region of cytoplasm
Genetic constraint (gnomAD): Loss-of-function variants: 6 observed, 15.52 expected, observed/expected ratio (o/e) 0.39, 90% interval 0.21 to 0.76. The upper end of that interval is the gene's LOEUF score, 0.76, which puts it in group 3 of 6, group 1 being the genes least tolerant of losing a copy. Missense variants: 118 observed, 139.97 expected, observed/expected ratio (o/e) 0.84, 90% interval 0.73 to 0.98. Synonymous variants: 42 observed, 49.07 expected, observed/expected ratio (o/e) 0.86, 90% interval 0.67 to 1.11.
Homologues: Orthologues: chimpanzee COPS8 (100% identical), macaque COPS8 (100% identical), dog COPS8 (98% identical), guinea pig COPS8 (98% identical), rat Cops8 (96% identical), mouse Cops8 (95% identical), pig COPS8 (95% identical), tropical clawed frog cops8 (77% identical).
Diseases named in the same sentence as COPS8 in open-access papers:
COPS8 is named in the same sentence as 52 diseases in open-access papers, as found by Europe PMC text mining. Sharing a sentence is not in itself a finding about the gene and the disease. The quoted sentences say what the papers report.
heart failure (6 papers, 2017 to 2024). Inability of the heart to pump blood at an adequate rate to meet tissue metabolic requirements. "Cardiac specific knockouts of Csn8 (also known as Cops8) led to a progressive dilated cardiomyopathy resulting in heart failure and death of all mice within 52 days." (PMID 33114658, 2020).
gastric cancer (5 papers, 2012 to 2018). A primary or metastatic malignant neoplasm involving the stomach. "COPS8 (COP9 signalosome subunit 8) encodes a highly conserved protein complex that has been reported to be associated with gastric cancer and kidney cancer." (PMID 30243023, 2018). "In gastric cancer cells, COPS8 has been reported to be part of G protein-coupled receptor pathway responsible for inhibiting the activation of NF-κB." (PMID 27448979, 2016). "We therefore focused on characterizing CARD10 and COPS8 as direct miR-146a targets and their roles in NF-κB activation in gastric cancer." (PMID 22992343, 2012). "To examine the effects of increased miR-146a levels in gastric cancer we identified two new miR-146a targets, CARD10 and COPS8, and investigated the roles of these targets." (PMID 22992343, 2012). "miR-146a expression is up-regulated in a majority of gastric cancers where it targets CARD10 and COPS8, inhibiting GPCR-mediated activation of NF-kappaB, thus reducing expression of NF-kappaB-regulated tumor-promoting cytokines and growth factors." (PMID 22992343, 2012). "We found that miR-146a is up-regulated in a mouse model of gastric cancer as well as in human gastric adenocarcinomas and identified CARD10 and COPS8 as new direct targets of miR-146a." (PMID 22992343, 2012). "In gastric cancer, in addition to its role in TLR/IL-1R signaling, miR-146a-5p has been reported to directly control the G-protein-coupled receptor-mediated activation of NF-κB, via caspase recruitment domain-containing protein 10 (CARD10) and COP9 signalosome complex subunit 8 (COPS8)." (PMID 28824448, 2017).
dilated cardiomyopathy (4 papers, 2020 to 2024). Cardiomyopathy which is characterized by dilation and contractile dysfunction of the left and right ventricles. "Cops8-cko causes massive cardiomyocyte death in the form of necrosis rather than apoptosis and rapidly leads to a progressive dilated cardiomyopathy phenotype as well as drastically shortened lifespan in mice." (PMID 34262479, 2021).
colitis (3 papers, 2022 to 2025). Inflammation of the colon. "Regulate the intestinal microbiota and activate the AhR—COPS8 pathway to improve colitis." (PMID 40282242, 2025).
melanoma (1 paper, 2022). A malignant, usually aggressive tumor composed of atypical, neoplastic melanocytes. "Receiver operating characteristic (ROC) curves showed an area under the curve (AUC) >90.0% for KPNA2, DTL, BACE2, DTYMK, E2F3 and SLC25A13, >80.0% for CCNA2, FOXM1, KIF4A, SLC45A2, COPS8, SLC45A13 and 70.0% for CDC25A and LINC00520; all significantly discriminating melanoma from benign nevi." (PMID 36320118, 2022).
meningioma (1 paper, 2020). A generally slow growing tumor attached to the dura mater. "As per the heatmap it is visible that NDRG1, MRC2, and COPS8 is highly abundant in the higher grades of meningiomas whereas more abundances of COL14A, COL12A1 were found in the non-tumor controls." (PMID 32974197, 2020).
COPS8 also shares sentences with these, for which no sentence is quoted: cancer (21 papers); tumor (16); colorectal cancer (8); breast carcinoma (4); atherosclerosis (2); cardiac hypertrophy (2); cardiovascular diseases (2); infection (2); acute myeloid leukemia (1); Alzheimer disease (1); autism (1); cardiomyopathies (1); cervical cancer (1); diffuse large B-cell lymphoma (1); digestive system tumor (1); Down syndrome (1); epithelial ovarian cancer (1); gastric adenocarcinoma (1); glioblastoma (1); glioma (1); head and neck squamous cell carcinoma (1); hepatocellular carcinoma (1); infections of the central nervous system (1); Insulin resistance (1); iron deficiency (1); kidney cancer (1); leukemia (1); liver cancer (1); lung squamous cell carcinoma (1); lymph node metastasis (1).
A further 16 diseases each share a sentence with COPS8 in 1 paper.